JAK2 (Janus kinase 2)
Diseases named in the same sentence as JAK2 in open-access papers (continued):
Sharing a sentence is not in itself a finding about the gene and the disease.
tumor (continued). "Essential signaling pathways involved in tumor cell proliferation and survival, such as epithelial growth factor receptor (EGFR) /Janus kinase 2 (JAK2)/ Signal transducer and activator of transcription 3 (STAT3) and mTOR pathways, have been reported to be propofol’s targets." (PMID 28962554, 2017). "STAT3 has been characterized as one of the major drivers of GBM, contributing to the maintenance of stemness and a mesenchymal phenotype via the IL-6/glycoprotein 130 (GP130)/STAT3 or EGF receptor (EGFR)/JAK2/STAT3 axis and leading to chemo- and radiation resistance of the tumor." (PMID 29340087, 2017). "All these results suggest that SOCS3 is a direct target of miR-222-3p, and exosomic miR-222-3p might enhance tumor malignancy through SOCS3 and its downstream effectors, such as the Jak2/Stat3 and Bcl-2 pathways." (PMID 28743280, 2017). "In the present study, preoperative serum CA125 level and mucin-16 expression in primary tumor tissues correlated with the nuclear levels of JAK2 protein, rather than its downstream effectors STAT3 or pSTAT3 (data not shown)." (PMID 27081079, 2016). "Thus, our results suggest that 4-MD inhibits the JAK2/STAT3 signaling, which in turn leads to suppression of tumor growth in vitro and in vivo." (PMID 26755649, 2016). "We could also show that leptin activates potent oncogenic pathways depending on JAK2/STAT3, AKT and ERK1/2 in the tumor cell line that carried a high-copy amplicon on the locus of the leptin receptor." (PMID 26871287, 2016). "Given the detoxifying role of GST isoforms upregulation in the absence of JAK2 potentially contributes to decreased oxidative damage and delayed tumour initiation in GHtgJAK2Δhep mice." (PMID 27713471, 2016). "Inhibition of Jak2 by G6 inhibits MCL1 via downstream inhibition of its transcription factors and therefore contributes further to enhancing induction of apoptosis and reducing tumor cell viability." (PMID 27056884, 2016). "JAK2 messenger RNA was high in the non-epithelial fraction of tumours and correlated with levels of TILs57, suggesting that activation of the JAK pathway in TILs is important to elicit the anti-tumour response." (PMID 27406745, 2016). "Moreover, activated JAK2/STAT3 increases AKT activation through the induction of AKT, while increased STAT3 and AKT activation leads to tumor development and EMT." (PMID 26515594, 2015). "We next examined whether BSN either alone or in combination with paclitaxel inhibits p-JAK1, p-JAK2, and p-Src in NSCLC tumor tissues." (PMID 25788267, 2015). "Astaxanthin, which is a non-provitamin A carotenoid predominantly distributed in microalgae, fungi, plants, and sea foods, is found to inhibit the onset of tumor progression by targeting signal transducer and activator of transcription 3 (STAT3)/Janus kinase 2 (JAK-2)." (PMID 26180591, 2015). "Furthermore, these cells have increased exposure to the factors necessary for tumor relapse, including CXCL12, through its receptors CXCR4 and CXCR7, IL6 through the Jak2/Stat3 pathway, EGF, FGF and IGF, among others." (PMID 25797268, 2015). "Additionally, Jak2 and STAT3 were analyzed to assess the involvement of these molecules in tumor growth suppression." (PMID 26084564, 2015). "This proof of principle study demonstrates that inhibition of the JAK2/STAT3 pathway by the addition of CYT387 suppresses the ‘stemness’ profile in chemotherapy-treated residual cells in vitro, which is replicated in vivo, leading to a reduced tumor burden." (PMID 24886434, 2014). "Dudley and colleagues reported the activation of JAK2/STAT5 in vascular ECs under low oxygen condition, and the activation may relate to the angiogenesis of neoplasm and retinopathy." (PMID 23516544, 2013).
tumor (continued). "In conclusion, our results suggested that the IL-17 mediated tumor-promoting role involved a direct effect on tumor cells through IL-6 induction by activating the AKT pathway; IL-6 in turn activated JAK2/STAT3 and up-regulated proinvasive factors IL-8, MMP2, and VEGF both in vitro and in vivo." (PMID 22171994, 2011). "In contrast, activated JAK2, as detected using P-JAK2-specific antibodies, was observed only in the epithelium of grades 1 and 3 tumours and was not present in the normal, benign and borderline tumours." (PMID 19088723, 2009). "A band corresponding to phosphorylated JAK2 appeared only when monocytes and tumor cells (MCF-7) were co-cultured together but not when either conditioned media or IL-10, were used (respectively)." (PMID 19718269, 2009). "Pacritinib and Fedratinib, both JAK2-selective inhibitors that display efficacy in myeloproliferative disorders, are being investigated for their relevance in solid tumors like BC and have shown promising results in reducing STAT3 activity and tumor progression in TNBC models." (PMID 41463071, 2025). "Although JAK2 and STAT3 expression levels were not significantly correlated with prognosis in this study, it is noteworthy that these two genes have been implicated in tumor microenvironment regulation in other cancer types." (PMID 40978029, 2025). "Furthermore, activating the JAK2/STAT3 pathway could induce programmed death-ligand 1 (PD-L1) expression, indicating that downregulating STAT3 could activate tumor immunity by inhibiting PD-L1 expression." (PMID 41280323, 2025). "We also observed that tumor cells that engaged senescence-related transcriptional programs, or “Sen-High” cells, upregulated IFN-γ signaling machinery, including Ifngr1, Ifngr2, Jak1, Jak2, Irf1, and Stat1, as well as IFN-γ target genes Cxcl9, Cxcl10, and Tap1." (PMID 40299790, 2025). "Therefore, we investigated whether the effects of MCPIP1 on tumor EMT and tumor stemness were mediated by targeting the IL6/JAK2/STAT3 signaling pathway." (PMID 40874680, 2025). "Notably, two new Tier IA events, absent in the primary tumor, were identified: an EGFR copy number gain (three copies) and a somatic JAK2 p.V617F mutation." (PMID 40842629, 2025). "Therefore, pharmacologically interrupting the JAK2/STAT3 signaling cascade emerges as a rational and promising strategy for developing anti‐HCC therapies that are capable of targeting both inflammation and tumor progression in an integrated manner." (PMID 41200213, 2025). "Given the synergistic effect of CHZ868 on CD19 CAR-T cells in JAK2 wild-type REH cells, we hypothesized that CHZ868 directly enhanced the anti-tumor function of CD19 CAR-T cells by modulating their characteristics during tumor interactions." (PMID 39891728, 2025). "In addition to a number of reported mRNA transcripts, such as ILEI, EGFR, MOESIN, FAM3C, JAK2 and EIF5A2, we identified ZEB2, an EMT‐related transcription factor that is vital for tumor metastasis, as a potential transcript regulated by PCBP1 at the translational level." (PMID 41117067, 2025). "However, the role of JAK2 in the human tumor immune microenvironment has not been comprehensively studied, and the relationship between JAK2 mutation and the immunotherapy response is unclear." (PMID 38200372, 2024). "Moreover, we found that FXR upregulates IL-6 and IL-6ST expression but not IL6Rɑ, thus suggesting that IL-6/IL-6ST may mediate FXR-modulated Jak2/STAT3 activation and tumor metastasis in NSCLC." (PMID 38360812, 2024). "CMTM family proteins exert their biological functions by regulating signaling pathways related to cell growth and migration, including the EGFR, WNT, and JAK2/STAT3 signaling pathways, suggesting that CMTM proteins may serve as potential targets for modifying tumor development." (PMID 38223763, 2024).
tumor (continued). "JAK2 inhibitors can transiently mask the intracellular signaling of the cytokine and the resulting toxicity, de facto creating a rapid and reversible pharmacological ON/OFF switch that localizes the activity of the payload to the tumor site while sparing healthy tissues." (PMID 38448543, 2024). "Importantly, the transient inhibition of JAK2 helped to control massive cytokine release, preserve liver integrity, and did not interfere with the potent anti-tumor activity of L19-mIL12 and its immunological effects at the neoplastic site." (PMID 38448543, 2024). "Taken together, PTPRO can downregulate JAK2/STAT3 phosphorylation, and inhibit oncogenic signals by suppressing expressions of Bcl-2 and Snail; these events may subsequently induce mitochondria-dependent apoptosis and suppress tumor metastasis." (PMID 38182570, 2024). "Importantly, gp130 was strongly correlated with JAK2 in tumor tissues, while it was moderately correlated with JAK2 in normal tissue." (PMID 38881895, 2024). "Furthermore, the expression of phosphorylated-JAK2, N-cadherin and VEGFA (by WB) was reduced in tumor tissues, indicating that Oridonin could suppress angiogenesis in vivo." (PMID 38791433, 2024). "However, no study has elucidated the specific molecular mechanisms by which the CXCL12/CXCR4/ACKR3 axis activates the JAK2/STAT3 pathway, and responses to the CXCL12/STAT3 signal transduction may vary across different tumor types and cell lines." (PMID 38920657, 2024). "Furthermore, because our group and others have demonstrated the importance of the JAK2/STAT3 pathway in the regulation of IBC cellular identity, stemness, and tumor progression, herein, we also investigated the modulation of STAT3 expression after MTDH knockout." (PMID 36902125, 2023). "Furthermore, by modulating the IL-6/JAK2/STAT3 signal pathway, FTO and APOE may limit the glycolysis of PTC, which could ultimately affect the growth of the tumor." (PMID 36831377, 2023). "Specifically, we experimentally determined whether Wnt/β-catenin and IL6-JAK-STAT3 signal pathways were activated in ccRCC by examining the expression of TTC13, β-catenin, JAK2, p-STAT3, STAT3 and p-JAK2 in ccRCC tumor tissues as well as the adjacent normal tissues." (PMID 37927783, 2023). "The IL6/JAK2/STAT3 signaling axis is best studied in the context of tumor metastasis and tumor pathology since it induces epithelial–mesenchymal transition (EMT), resulting in tumor metastasis by promoting the expression of EMT-inducing transcription factors, such as Snail, ZEB1, JunB, and Twist1." (PMID 38203502, 2023). "Additionally, GNAQ, GNAS, JAK2, NRAS, IDH2, and CTNNB1 are cancer-related genes that may be related to tumor metastasis." (PMID 36780540, 2023). "The activation of REG3A will enhance the JAK2/STAT3 pathway and form a positive feedback loop of REG3A-JAK2/STAT3, thereby amplifying the carcinogenic effect of IL-6/JAK2/STAT3, and ultimately leads to excessive PC cell proliferation in vitro and in vivo and tumor formation." (PMID 36591515, 2022). "Therefore, the inhibition and regulation of IL-6/JAK2/STAT3 signaling pathway is conducive to the prevention and treatment of tumors and the improvement of prognosis, and it is also one of the important targets for screening anti-tumor drugs." (PMID 36591515, 2022). "In addition to PD-L1, EVs transported to Mφs can promote the expression of cytokines IL-6, IL-10, and MCP-1 by activating the Janus kinase 2-signal transducer and activator of transcription 3 (JAK2/STAT3) pathway, leading to immunosuppression of Mφs and promotion of tumor development." (PMID 36032078, 2022). "Therefore, suppression of the JAK2/STAT3 pathway could shed new light on cancer treatment and afford new targets for tumor therapy." (PMID 36104717, 2022).
tumor (continued). "Similar frequencies of JAK1, JAK2, and STAT3 genotypes were seen in patients stratified by age, phototype, nevi presence, sun exposure, sunburn episodes, type of sun exposure, tumor location, ulceration, type of growth, Clark level, Breslow thickness, clinical stage, and metastases." (PMID 35982955, 2022). "Notably, DHCT treatment of HCC cells resulted in the reduced expression of α7nAChR, JAK2, and cancer stemness markers (CD133, KLF4, and SOX2) as well as decreased ALDH1 activity, thereby suppressing the colony-forming and tumor sphere generation abilities of HCC cells." (PMID 35111269, 2022). "The JAK2/STAT3 pathway participates in cancer cell survival, proliferation and progression by regulating multiple processes, such as epithelial–mesenchymal transition (EMT), which is required for tumor metastasis, and molecular signals that control other cancer hallmarks." (PMID 33805840, 2021). "At the same time, inhibition of miR-216a-5p or IL-6 induced cells after tumor cell stemness transformation is promoted, and the effect of LNT is reversed, indicating that LNT is involved in cell stemming by regulating miR-216a-5p targeting and mediating the JAK2/STAT3 signaling pathway." (PMID 34900727, 2021). "Thus, we confirm that UCHL3 is a deubiquitinase for JAK2-phosphorylated BRD4, whose overexpression in CRC may provide a mechanism to maintain the BRD4 protein abundance in an inflammatory tumor microenvironment." (PMID 34290255, 2021). "Despite this fact, amplification of 9p24.1 (locus-containing JAK2/PDL1/PDL2), a frequently observed cytogenetic abnormality in classical HL patients, induces aberrant overexpression of PD-L1 on tumor cells, suggesting that tumor PD-L1 might dampen anti-tumor immunity." (PMID 32787882, 2020). "Our data showed that nevirapine inhibited distant metastasis of tumor xenografts and phosphorylation of pJAK2 and pSTAT3 proteins in WRO 82‐1 cells, indicating that nevirapine exerts its anticancer effects possibly by inhibiting IL‐6/JAK2/STAT3 signaling pathway." (PMID 31631580, 2019). "In addition, other potential therapeutic targets, such as PIK3CA and JAK2, may be explored in EBV-positive tumours." (PMID 31790410, 2019). "Chromosome 1q21.3, encoding IRAK1, is amplified in recurrent BC; S100A7/8/9 and IRAK1 drive tumorsphere growth, disrupted by pacritinib via IRAK1, not JAK2; pacritinib TGI in xenograft models via IRAK1; pacritinib + paclitaxel caused durable tumor regressions in a neoadjuvant TNBC model." (PMID 30279971, 2018). "Ruxolitinib failed to inhibit tumour progression in JAK2 amplified TNBC cells." (PMID 29298879, 2018). "However, whether SOCS1 and JAK2/STAT3 pathway participate in the proangiogenic switch of CAFs and whether tumor-secreted exosomal miRNAs regulate both regulators are unclear." (PMID 30285793, 2018). "By Sanger sequencing we found a JAK2 c.2876A>C exchange to be present in Ma-Mel-54a cells that, however, could not be detected in the corresponding tumour tissue." (PMID 28561041, 2017). "Deletions of PD-L1 (CD274) and PD-L2 (PDCD1LG2) genes were always accompanied by JAK2 deletion, suggesting that JAK2 deletion may be a mechanism to safeguard tumor cells from activated cytotoxic T cells in the absence of negative regulators PD-L1/PD-L2." (PMID 28977839, 2017). "Recent studies further showed that mutation of JAK2 was capable of inducing BCL, and inhibition of JAK2 decreased IgM-induced STAT3 phosphorylation and increased apoptosis of tumor cells in a dose-dependent manner, which suggest that JAK2 could be a target for the treatment of BCL." (PMID 29340070, 2017). "Thus, as an inhibitor of JAK2/3-STAT3 signaling, physalin A, has potent anti-tumor activities, which may facilitate the development of a therapeutic strategy for treating NSCLC." (PMID 26843613, 2016).
tumor (continued). "To test whether inhibition of the JAK/STAT3 pathway would affect the growth of pediatric solid tumors, we evaluated the anti-tumor activity of AZD1480, an ATP competitive inhibitor of JAK1 and JAK2, which has been shown to decrease the growth of adult tumors in several pre-clinical models." (PMID 23531921, 2013). "Furthermore, our data predict that intermittent treatment with anti-Jak2/STAT5 may inhibit newly formed early lesions and further delay tumor appearance or may even completely prevent cancer in some of them." (PMID 24381245, 2013). "Additionally, considering the expanding clinical applications of tumor immunology, our review offers a more comprehensive understanding of the correlation between CMTM family and immunity, encompassing various mechanisms, including PD-L1/PD-1, EGFR, WNT, and JAK2/STAT3 pathways." (PMID 38223763, 2024). "Additionally, cucurbitacin B can inhibit the JAK2/STAT3 signaling pathway, reduce the migration and invasion ability of M2-like TAM polarization-induced colon cancer cells, enhance the anti-tumor response, and increase the expression of CD4 and CD8 in the tumor microenvironment." (PMID 39275042, 2024). "However, independent studies confirm that its expression in the MDA-MB-231 cell line not only favors tumor growth but also promotes the Warburg effect and induces resistance to paclitaxel and inhibitory molecules of the PI3K/AKT/mTOR pathway through activation of JAK2/STAT3." (PMID 36901916, 2023). "Because tumor cells rely upon constitutive activation of STAT5, ERK-1/2 (Extracellular signal-regulated kinase 2), and AKT signaling pathways, targeting down-stream JAK2 targets, such as Pim kinases may have significant benefits in preventing JAK2 inhibitor resistance." (PMID 36694243, 2023). "Similarly, no p-STAT6 and p-JAK2 staining appeared in the primary tumor cells." (PMID 34090412, 2021). "In addition, the anti-tumor effects of JAK2/3 inhibitor AG490 was observed in WT mice but not in Rab37 KO mice, consistent with the hypothesis of Rab37/IL-6/STAT3/PD-1 functioning in the same axis." (PMID 34093869, 2021). "In prostate cancer lacking PTEN, activated JAK2/STAT3 signaling established an immunosuppressive tumor microenvironment via SASP factors such as CXCL1, CXCL2, and IL-6 and resulted in tumor growth and chemoresistance." (PMID 40862837, 2025). "The type II selective JAK2 inhibitor, CHZ868, did not compromise the anti-tumor efficacy of CD19 CAR-T cells." (PMID 39891728, 2025). "JAK2/STAT3 belongs to non-receptor tyrosine kinases, playing a crucial role in the proliferation and apoptosis of tumor cells." (PMID 37895015, 2023). "CM also reduced the expression of JAK2 mRNA and STAT3 mRNA, although not significantly (P > 0.05), and reduced PD-L1 mRNA in tumor tissue compared to the control group (P < 0.05)." (PMID 38116545, 2023). "Of interest, we identified the top 10 differentially mutated genes between APOBEC-enriched and non-APOBEC-enriched samples, and among these, KRAS, CDHR5, JAK2, and MAP2K4 were previously shown to be closely related to tumor development." (PMID 32670354, 2020). "Indeed, recent studies showed that human ccRCC cell lines were sensitive to Jak2-STAT pathway activity induced by dimethoxycurcumin, and recent clinical data suggested that the effects of drugs regularly used to treat RCC might elicit their anti-tumor effects via targeting of the STAT pathway." (PMID 29348897, 2017). "Taken together, we show high constitutive STAT3 phosphorylation in primary tumour samples from patients with SCLC but not from NSCLC, and constitutive and CXCL12-dependent activation of the JAK2/STAT3 pathway in SCLC cell lines." (PMID 19455144, 2009). "However, when tumor cells are divided in tumor tissue with and without HIF1A expression, statistical significance was observed in JAK2 expression." (PMID 40332447, 2025).